IL4 (interleukin 4)
Diseases named in the same sentence as IL4 in open-access papers (continued):
Sharing a sentence is not in itself a finding about the gene and the disease.
gallstones (2 papers, 2011 to 2021). Solid crystalline precipitates in the biliary tract, usually formed in the gallbladder, resulting in the condition of cholelithiasis. "Low levels of IL-4 are a predisposing factor to gallstone formation." (PMID 34449702, 2021). "IL-4 deficiency in mice predisposes them to gallstone formation." (PMID 34449702, 2021). "The correlations between IL-4 and IL-6, as well as between IL-6 and IL-7, suggest that the initiated inflammatory response to gallstone induced injury is being actively intensified and sustained through cytokines modulated intercellular signalling pathway." (PMID 34449702, 2021). "IL-4 also has anti-inflammatory properties, and it has been previously shown that IL-4 concentration in patients with gallstones is lower than in healthy individuals." (PMID 34449702, 2021). "All our patient samples are affected by gallstone induced cholecystitis, thus, the inflammation itself could be the reason of elevated IL-4 in the tissues, and it could work as a negative regulator of inflammation." (PMID 34449702, 2021).
gastroenteritis (2 papers, 2017 to 2024). An inflammatory disorder that affects the upper and lower gastrointestinal tract. "JunB is a transcription factor that promotes the expression of Th2 cytokines IL-4 and IL-5, Therefore, blocking the production of IL-4 and IL-5 may be one of the targeted mechanisms of Th-cell associated gastroenteritis and IBD." (PMID 39185411, 2024).
glomerular disease (2 papers, 2012 to 2018). "In this study, B-cell derived IL-4 results in podocyte damage and proteinuria in mouse and activation of IL-4 signaling in glomeruli is observed in a significant proportion of patients with glomerular disease." (PMID 30083135, 2018). "The findings suggest that the immune imbalance with dominant Th2 cells, which causes the abnormal levels of interferon-gamma (INF-γ) mainly secreted by Th1 cells and interleukin-4 (IL-4) by Th2 cells, contributes to the glomerular disease through promoting proteinuria." (PMID 22675377, 2012).
glomerulosclerosis (2 papers, 2021 to 2022). A hardening of the kidney glomerulus caused by scarring of the blood vessels. "In a different model of IL-4 transgenic B6C3F1 mice, mice developed glomerulosclerosis associated with collagen deposition." (PMID 35444658, 2022). "Of note, IL-4 seems to be involved in glomerulosclerosis via direct interaction with kidney cells." (PMID 35444658, 2022).
gonococcal infection (2 papers, 2018 to 2019). "Furthermore there was no IL-4 response, and IL-17 responses induced by the gonococcal infection itself remained unaltered." (PMID 29404418, 2018).
gout (2 papers, 2019 to 2024). A condition characterized by painful swelling of the joints, which is caused by deposition of urate crystals. "Cytokine levels, including IFN-γ, TNF-α, IL-2, IL-4, IL-6, IL-10 and IL-17, were detected in early-onset gout, late-onset gout and HCs." (PMID 38240927, 2024). "Additionally, gout patients had significantly higher cytokines levels (including IL-2, IL-4, IL-6, IL-10, IL-17, IFN-γ, and TNF-α) than HCs; IL-2 levels were positively correlated with Treg cells and negatively correlated with ESR." (PMID 38240927, 2024). "Nonetheless, we found higher plasma levels of IL-1β, IL-1ra, IL-4, IL-6, IL-8, IL-9, IL-13, IL-17, FGF-basic, IFNγ, and TNFα in acute gouty arthritis patients." (PMID 31739430, 2019). "Then, we compared cytokine levels, including IFN-γ, TNF-α, IL-2, IL-4, IL-6, IL-10 and IL-17 among gout with tophus, gout without tophus and HCs." (PMID 38240927, 2024).
gram-negative bacterial infections (2 papers, 2024). Infections caused by bacteria that show up as pink (negative) when treated by the gram-staining method. "Other studies have shown that IL-4 and TNF-α have a dual role in resisting Gram-negative bacterial infections in the organism." (PMID 38764854, 2024).
hand eczema (2 papers, 2021 to 2023). A form of contact dermatitis characterised by inflammation, redness and itching of the hands. "Two major classes of drugs emerging for the treatment of hand eczema include IL-4/IL-13 inhibitors and JAK inhibitors." (PMID 37496489, 2023).
hemorrhagic cystitis (2 papers, 2018 to 2019). Inflammation of the bladder resulting in bloody urine. "Prior work suggests that IL-4 alleviates ifosfamide-induced hemorrhagic cystitis (IHC), but systemically administered IL-4 causes significant side effects." (PMID 29613835, 2018). "Nevertheless, evidence suggests that IL-4-associated anti-inflammatory pathways and targets thereof are promising therapeutic candidates for hemorrhagic cystitis." (PMID 29613835, 2018). "The Schistosoma hematobium homolog of IL-4-inducing principle from Schistosoma mansoni eggs (H-IPSE) is a molecule that may modulate S. hematobium-associated hemorrhagic cystitis and broader host bladder biology." (PMID 29613835, 2018). "Cytokines, particularly IL-4, appear to play an important role in chemotherapy-induced hemorrhagic cystitis (CHC) and thus, are promising therapeutic strategies." (PMID 29613835, 2018). "Having demonstrated that H06 H-IPSE shares several features with M-IPSE, including activating IgE-bearing basophils to produce IL-4 and localizing in host cell nuclei, we next sought to determine any in vivo effects of H06 H-IPSE in the ifosfamide-induced mouse model of hemorrhagic cystitis." (PMID 29613835, 2018). "However, systemic administration of IL-4 is unlikely to be an acceptable prophylactic or therapeutic approach for cyclophosphamide-induced hemorrhagic cystitis and IHC." (PMID 29613835, 2018).
hemorrhagic stroke (2 papers, 2018 to 2023). A stroke caused by a bleed on the brain. "Several previous studies have reported that STAT3-deficient microglia upregulate IL-4-based anti-inflammatory cytokine expression after hemorrhagic stroke, which implies a protective phenotype against neuroinflammation." (PMID 37552127, 2023). "In CSF, IL-4 wasfound to be higher in survivors than in non-survivors during the first 24 hoursfollowing hemorrhagic stroke (34.98 versus 0.001pg/mL; p =0.04)." (PMID 29742229, 2018). "Interleukin 4 levels within the cerebrospinal fluid duringthe first 24 hours after hemorrhagic stroke were found to be higher insurvivors than in non-survivors." (PMID 29742229, 2018).
Hepatic failure (2 papers, 2005 to 2022). "Analyses of serum revealed elevation of proinflammatory cytokines (TNF alpha, IL-6), cytokines (IL-2R), anti-inflammatory cytokines (IL-4) and chemokines (IL-8) as well as signs of rhabdomyolysis and hepatic failure." (PMID 16285034, 2005). "The levels of cytokines, such as IL-10, IL-2, IL-4, IL-6, IFN-γ, and GM-CSF in PBC patients who developed liver failure, were significantly reduced, and the difference in IL-2 between the two groups was statistically significant (P=0.028)." (PMID 36159788, 2022).
Histiocytosis (2 papers, 2019 to 2022). An excessive number of histiocytes (tissue macrophages). "However, IL-4 is not totally an anti-inflammatory agent: in vivo studies correlated chronic high dosage and/or overproduction of IL-4 with weight loss, decreased pro-inflammatory cytokine production, histiocytosis and increased IFN-gamma production." (PMID 35208588, 2022). "In vivo studies have revealed that chronic high dosage or transgenic overproduction of IL-4 results in accumulation of AAMΦs, increased IFN-γ expression, decreased pro-inflammatory cytokine production, histiocytosis, erythrophagocytosis, extramedullary hematopoiesis, and weight loss." (PMID 31757102, 2019).
hypercorticism (2 papers, 2016 to 2020). "Consequently the data suggests that acute IMO-induced hypercorticism may contribute to downregulation of IL-4 production in the LC and this decrement of IL-4 level leads to behavioral change." (PMID 26903707, 2016).
idiopathic interstitial pneumonia (2 papers, 2005 to 2011). A class of diffuse lung diseases that typically affect the pulmonary interstitium, although some also have a component affecting the airways (for instance, Cryptogenic organizing pneumonitis). "This increased level of IFNγ in NSIP, would be expected to counteract the postulated pro-fibrotic effect of IL-4 and may help explain the relative lack of fibrotic foci in this form of idiopathic interstitial pneumonia." (PMID 16287509, 2005).
idiopathic membranous nephropathy (2 papers, 2022 to 2023). "These cells produce interleukin 4 (IL-4) and IgG4, which can deposit in the microvasculature and basement membrane of the glomerulus, leading to the development of membranous GN." (PMID 37239388, 2023).
interstitial cystitis (2 papers, 2015 to 2021). A rare chronic debilitating urogenital disease characterized by urinary frequency, urgency, and pelvic pain. "Interstitial cystitis/painful bladder syndrome (IC/PBS) is characterized by increased bladder pain and urinary frequency and associated with increased IL-2, IL-6, IL-8, TNFα expression, and lowered levels of IL-4." (PMID 25962909, 2015).
intervertebral disc degeneration (2 papers, 2015 to 2024). "Although the tensile stress on disc cells have been studied in vitro, some cytokines including TNF-α, interleukin-1(IL-1), nitric oxide (NO), interferon (IFN)-γ, and interleukin-4 (IL-4) have been reported to promote the deterioration of intervertebral disc degeneration." (PMID 25886263, 2015).
intestinal parasite infections (2 papers, 2023). "An increase in age has been shown to be correlated with a reduction in intestinal parasitic infections, which subsequently leads to a lower activation and secretion of the anti-helminthic cytokine IL-4." (PMID 37111135, 2023).
Intussusception (2 papers, 2020 to 2025). An abnormality of the intestine in which part of the intestine invaginates (telescopes) into another part of the intestine. "Levels of serum cytokines on admission, including interleukin (IL) 2, IL-4, IL-6, tumor necrosis factor α (TFN-α), and interferon γ (IFN-γ) were rarely increased, except that 1 critically ill patient with underlying intussusception had an IL-6 level of 3868.86 pg/mL." (PMID 32492165, 2020).
invasive carcinoma (2 papers, 2007 to 2025). A carcinoma that is not confined to the epithelium, and has spread to the surrounding stroma. "Releasereached a maximum for IL-10 and IL-4 in patients with CIN III and decreasedsignificantly for both cytokines in patients with invasive carcinoma.(K. W. test: P=.019 for IL-10 and P=.033 for IL-4)." (PMID 18288269, 2007).
joint disease (2 papers, 2005 to 2018). "IL-4 mRNA expression underwent a significant burst on day 3 of AIA, that is, at the end of the acute phase of the joint disease." (PMID 15899031, 2005). "Plasma levels of IL-4 and the Th2-related chemokine eotaxin have also been shown to be elevated in both male and female subjects with no prior symptoms of joint disease who later develop RA." (PMID 30029616, 2018).
keratitis (2 papers, 2022 to 2026). A corneal disease that is characterized by inflammation of the cornea. "IL-4 has also been shown to enhance TSLP expression in a mouse model of keratitis induced by Aspergillus fumigatus." (PMID 41576028, 2026). "IL-4 KO mice presented reduced keratitis that correlated with impaired eosinophil recruitment to the cornea, while IL-12-treated mice experienced enhanced eosinophil recruitment and excessive pathology." (PMID 36389745, 2022).
kidney tumor (2 papers, 2019 to 2024). "Here, we have investigated the activation of the JAK-STAT signaling pathway in three pediatric kidney tumor cell lines (WT-CLS1, WT-3ab and G-401) and demonstrated that several STAT proteins are activated in these cell lines in response to IFN-α, IFN-γ, IL-6 and IL-4." (PMID 38396958, 2024). "In addition, CD46 also seems to be a connection point of the innate and adaptive immune system, and itself is also regulated by various inflammatory cytokines like IL-1beta, IL-4, and TGF-β, which downregulate CD46 expression in RPTECs and renal tumor cell lines." (PMID 30958843, 2019).
knee osteoarthritis (2 papers, 2017 to 2019). "Also, plasma levels of the anti-inflammatory cytokines IL-4, IL-7, IL-10, and IL-13 seem to increase after exercise in healthy subjects and IL-10 also in patients with knee-osteoarthritis." (PMID 28243900, 2017).
leiomyoma (2 papers, 2014 to 2021). A well-circumscribed benign smooth muscle neoplasm characterized by the presence of spindle cells with cigar-shaped nuclei, interlacing fascicles, and a whorled pattern. "Numerous studies described leiomyoma cells exhibiting a significantly greater expression of IL1, IL4, IL5, IL6, IL10, IL11, IL13, and IL15." (PMID 34442017, 2021).
lepromatous leprosy (2 papers, 2019 to 2023). A chronic communicable infection which is a principal or polar form of leprosy. "Lepromatous leprosy patients showed significantly lower IFN-γ and higher IL-4 levels in culture supernatant and significantly low expression of IFN-γ and higher expression of IL-4 by CD4+ T cells than healthy individuals with or without antigenic stimulation." (PMID 30642265, 2019).
Leukopenia (2 papers, 2020). "In vivo experiments showed that APS-II can improve the leukopenia caused by cyclophosphamide and increase the IL-2, IL-4, and INF-γ levels in mice sera." (PMID 33390949, 2020).
liver abscesses (2 papers, 2015 to 2016). "IL-4 supports the generation of Th2 cells, which simultaneously activate B cells to induce systemic immune responses and yield antibodies to protect against the development of liver abscesses." (PMID 26824828, 2016).
lymphoid neoplasm (2 papers, 2019 to 2021). A neoplasm composed of a lymphocytic cell population which is usually malignant (clonal) by molecular genetic and/or immunophenotypic analysis. "DOCK10 expression is induced by IL-4 in CLL and normal B cells, but it is not known whether this occurs in other lymphoid neoplasms." (PMID 34449554, 2021).
malignant pleural mesothelioma (2 papers, 2014 to 2021). A malignant neoplasm that arises from mesothelial cells in the pleura and shows a diffuse growth pattern. "A study of intraperitoneal (i.p.)injection of pan-ErbB/IL-4 CAR T cells targeting patient-derived malignant pleural mesotheliomas xenografts in SCID mice showed tumor regression or cure in all mice." (PMID 34680456, 2021). "It has been shown that the natural immune reaction to human malignant pleural mesothelioma involved tumor infiltrating T cells which are skewed toward an IL-4-producing phenotypes." (PMID 25208941, 2014).
MALT lymphoma (2 papers, 2009 to 2015). An indolent, extranodal type of non-Hodgkin lymphoma composed of small B-lymphocytes (centrocyte-like cells). "In summary, analysis of Th1/Th2 cytokine levels in serum samples shows that IL-8 levels were elevated in GI FL and MALT lymphomas, whereas IL-4 and IL-1β levels were elevated in MALT lymphomas." (PMID 26674732, 2015). "Serum IL-4 and IL-1β levels were elevated in MALT lymphoma cases compared with healthy controls (P = 0.00019 and 0.024, respectively)." (PMID 26674732, 2015). "Serum IL-8 levels were elevated in GI-FL and MALT lymphomas, and serum IL-4 and IL-1 β levels were elevated in MALT lymphomas." (PMID 26674732, 2015). "In the present study, elevation of IL-4, IL-1β, and IL-8 levels was detected in MALT lymphomas." (PMID 26674732, 2015). "In contrast to IL-8RB, IL-4RA was weakly positive for more than half of the cases regardless of the subtypes (P = 0.63) and was not reflected high serum IL-4 value in MALT lymphoma." (PMID 26674732, 2015). "In the present study, GI FL and MALT lymphoma had similar elevations in serum IL-8; to discriminate MALT from GI FL, IL-4 and 1β elevations could be used." (PMID 26674732, 2015).
Mikulicz disease (2 papers, 2015 to 2022). "The expression levels of IL-4, IL-5, IL-10, TGF-β, and FoxP3 mRNA in labial salivary glands of patients with Mikulicz's disease have been shown to be higher than the levels in healthy persons." (PMID 35769404, 2022).
mouth ulcers (2 papers, 2016 to 2024). "The expression levels of IL-4, MMP-19, and Activin A are closely related to the occurrence of oral ulcers." (PMID 27375764, 2016).
mucormycosis (2 papers, 2021 to 2022). "Activation of the IL-4/IL-13 pathway was previously shown to play an important role in air-way hyperactivity associated with allergen-induced hypersensitivity, a condition characteristic of mucormycosis." (PMID 35387075, 2022).
Myalgia (2 papers, 2014 to 2023). "Arthralgia was associated with high IL-4 levels (p = 0.0388), whereas myalgia was linked to increased IL-10 levels (p = 0.0114)." (PMID 37235332, 2023). "Moreover, arthralgia and myalgia in our patients were linked to increases in IL-4 (p = 0.0388) and IL-10 (p = 0.0114), respectively." (PMID 37235332, 2023).
mycobacterial infection (2 papers, 2011 to 2023). "Th2 (IL-4) response was insignificant at all time points post booster, but it was found to be increased by 4th and 8th week post challenge with Mycobacterium infection in all groups presumably due to onset of the disease (data not shown)." (PMID 21853054, 2011). "Overall, fdr mutant-infected MΦ exhibited a pro-inflammatory cytokine profile that included IL-4 and IFN-γ, two cytokines important for the control of mycobacterial infection and inflammation in the host." (PMID 37764917, 2023).
myeloid leukemia (2 papers, 2022 to 2025). A clonal proliferation of myeloid cells and their precursors in the bone marrow, peripheral blood, and spleen. "In our study, IL-4 could induce the expression of M2 markers including IL-10, TGF-β, and CD163 as well as some chemokines including CCL-17 and CCL-22 in human myeloid leukemia mononuclear THP-1 cells." (PMID 35996149, 2022).
myositis (2 papers, 2022 to 2023). "Increased IL-1α, IL-21, LIF, and PIGF-1 levels were significantly associated with myositis incidence, while the serum levels of six cytokines (BTLA, GM-CSF, IL-4, PD-1, PD-L1 and TIM-3) were higher in patients with rash." (PMID 36159840, 2022). "Increased IL-1α, IL-21, LIF, and PlGF-1 levels were significantly associated with the incidence of myositis, and the serum levels of six cytokines (BTLA, GM-CSF, IL-4, PD-1, PD-L1 and TIM-3) were higher in patients who developed a rash." (PMID 36159840, 2022).
nicotine addiction (2 papers, 2023 to 2026). "Our results also suggest that the mode of IL-13 (or IL-4) production and release in the CNS may affect motivation and vulnerability to nicotine addiction." (PMID 40775068, 2026). "While, IL‐1 and IL‐4 pathway, negative regulation of acute inflammatory response, regulation of mitochondrial translation, superoxide metabolic process, nitric oxide‐mediated signal transduction and nicotine addiction were enriched after treatment with CSE + HNK as compared with CSE treatment alone." (PMID 37795870, 2023).
Opportunistic infection (2 papers, 2019 to 2025). An infection that is caused by a pathogen that would generally not be able to cause an infection in a host with a normal immune system. "Thus, our findings suggest that ETEC's presence in the gut might induce il4 transcription in the lung as a defense strategy to prevent potential opportunistic infections." (PMID 40302745, 2025).
orofacial cleft (2 papers, 2021 to 2023). A disorder of facial skeleton that is characterized by cleft lip and/or cleft palate that result in feeding, speech and hearing problems caused by failures during development. "The complex and intertangled interactions between various cytokines, along with varied dual roles of certain cytokines (IL-4 and 6), can play a pivotal role in the pathogenesis and manifestation of orofacial clefts." (PMID 33673258, 2021).